STAT3 (signal transducer and activator of transcription 3)
Diseases named in the same sentence as STAT3 in open-access papers (continued):
Sharing a sentence is not in itself a finding about the gene and the disease.
glioblastoma (continued). "For example, EZH2 can methylate non-histone substrates such as STAT3 inducing the tumorigenicity in glioblastoma stem-like cells and melanoma." (PMID 27793053, 2016). "This is associated with β-catenin/TCF4 and STAT3 downregulation, which can, in turn, suppress EZH2 expression representing a negative feedback loop that is deregulated in glioblastoma leading to uncontrolled cell cycle progression." (PMID 27793053, 2016). "LP resveratrol-treated glioblastomas showed less Cyclin D1 staining, enhanced autophagy with up-regulated LC3 and Beclin1 expression, and widely distributed apoptotic foci around tumor capillaries with suppressed STAT3 expression and nuclear translocation." (PMID 27716625, 2016). "Furthermore, in glioblastoma patient samples, we found that the levels of EGFRvIII, PEDF, p-STAT3, and NICD proteins were highly correlated." (PMID 25992628, 2015). "The cancer-initiating cells in glioblastoma were shown to be promoted to self-renew by TGF-β via the induction of LIF, a cytokine of the IL-6 family, which induces self-renewal of embryonic stem cells via activation of STAT3." (PMID 23998913, 2013). "Several pathways have been suggested to mediate the highly migratory phenotype of glioblastoma cells, including signaling via Focal adhesion kinase (FAK), Phosphoinositide 3-kinase PI3K and Signal transducer and activator of transcription 3 (STAT3)." (PMID 22719241, 2012). "LN-18 glioblastoma cells are insensitive to resveratrol due to the more inducible brain-associated SULT expression, insufficiency of resveratrol to suppress activated STAT3 signaling and the lack of PIAS3 nuclear translocation." (PMID 22096581, 2011). "First, to investigate whether STAT3 and upstream kinases JAK1/2 are activated in U251 cells, we performed western blot and showed a higher expression of pSTAT3 Tyr705 and pJAK2 in the glioblastoma cell line U251 than in NHA." (PMID 21906308, 2011). "Overexpression of the gene encoding the epidermal growth factor receptor (EGFR) occurs commonly in glioblastoma, leading to activation of downstream kinases including phosphatidylinositol 3'-kinase (PI3K) and signal transducer and activator of transcription 3 (STAT3)." (PMID 20113523, 2010). "Therefore, resveratrol’s ability to modulate JAK-STAT signaling, especially through STAT3 inactivation, highlights its potential as a therapeutic agent in combination with TMZ for treating glioblastoma, potentially overcoming chemoresistance and improving patient outcomes." (PMID 39769099, 2024). "In this study, novel pyrimidine compounds, BY4003 and BY4008, were synthesized to target the JAK3/STAT3 signaling pathway, and their therapeutic efficacy and mechanisms of action were evaluated and compared with Tofacitinib in U251, A172, LN428 and patient-derived glioblastoma cells." (PMID 39153914, 2024). "Analysis of ligand-receptor pairs suggests that oncostatin M in macrophages activates STAT3 signaling to induce a mesenchymal GBM cellular state via interaction with its receptors (or leukemia inhibitory factor receptor, in complex with GP130) in glioblastoma cells." (PMID 36229714, 2023). "We also mined the clinical data of glioblastoma cohorts in TCGA, PanCancer Atlas and found that alterations in mTOR, STAT3, and CDK6 constituted 5% of the genetic alteration occurring in GBM patients." (PMID 34572040, 2021). "Our results revealed that STAT3 expression was positively correlated with infiltration of macrophages, dendritic cells, CD4+ T cells, CD8+ T cells, neutrophils, and B cells (all r > 0.06, p < 0.005) in all cancer types analyzed, with the exception of glioblastoma multiforme (GBM)." (PMID 33668805, 2021).
glioblastoma (continued). "However, in contrast to myeloma cells, the STAT3 transcription factor does not induce LINC00152 expression in A172 glioblastoma cells." (PMID 34531451, 2021). "Given that RRAD induces EGFR and STAT3 activation and RRAD knockdown sensitizes chemoresistant cancer cells to cytotoxic drugs, targeting STAT3 with oxelaidin or butamirate may attenuate temozolomide resistance and glioblastoma recurrence after treatment." (PMID 33980886, 2021). "We did not observe any downstream signalling events in HEK293T, COS-7 or HUVEC cells, indicating that the interaction between ADGRL4/ELTD1 and the JAK/STAT3/HIF-1α pathway is specific for glioblastoma or other cancer cell types and does not apply within endothelial cells." (PMID 33893326, 2021). "STAT3 activation by US28-mediated IL-6 secretion was also reported to be involved in VEGF production in NIH-3T3 cells stably transfected with US28 and U373MG cells 48 h after infection with HCMV as well as in primary glioblastoma specimens from patient samples." (PMID 32779712, 2020). "In a study, treatment of DMC prior to TMZ in glioblastoma cells resulted in a significant increase in caspase-3 signaling, mitochondria-related apoptosis and a marked inhibition of cell growth in vitro through production of ROS as well as inactivation of JAK/STAT3 signaling pathway." (PMID 33217990, 2020). "Notably, primary glioblastoma tumours contain both US28 and activated STAT3." (PMID 32779712, 2020). "For example, in glioblastoma (GBM) and melanoma, EZH2 mediates the lysine methylation of STAT3, leading to its activation, which enhances tumorigenicity." (PMID 32448308, 2020). "Notably, targets of these miRNAs might be involved in glioblastoma signaling (PI3K signaling pathway), STAT3 Pathway, TGF-β, ERK5, Rho Family GTPases, PTEN, ERK/MAPK, and EGF pathways." (PMID 29455644, 2018). "In addition, EZH2 can also methylate non-histone proteins like STAT3, leading to enhanced STAT3 activity and an increase in tumorigenic potential of glioblastoma stem-like cells." (PMID 30619733, 2018). "However, we clearly detected reduced STAT3 activation in Rac down-regulated glioblastoma cells, but not STAT5 activation (data not shown)." (PMID 28160553, 2017). "Interestingly, although STAT3 inhibition induces neural genes, such as FGF21 and GDF15, neither Jmjd3 overexpression or STAT3 inhibition are sufficient to drive differentiation of the glioblastoma stem cells." (PMID 28384648, 2017). "Interestingly, it was reported that inhibition of PI3 kinase (PI3K) activity, which in turn inhibited AKT activation, significantly increased the DNA-binding activity of STAT3 in human glioblastoma U87and D54 cells without increasing STAT3 phosphorylation." (PMID 27418138, 2016). "The expression of STAT3, a master regulator of stemness, also decreased following BIS depletion concomitant with decreases in the nuclear levels of active phosphorylated STAT3, while ectopic STAT3 overexpression resulted in recovery of sphere-forming activity in BIS-knockdown glioblastoma cells." (PMID 27145367, 2016). "Therefore, the authors believe that the STAT3 signal is not a downstream target of the PI3K/Akt pathway in the glioblastoma cell line." (PMID 25405202, 2014). "In another study, it was found that STAT3 activation by BMX (bone marrow X-linked), a non-receptor tyrosine kinase, is required for maintaining the self-renewal and tumorigenic potential of cancer stem cells in glioblastoma." (PMID 24995504, 2014). "Furthermore, the overexpression of WT-STAT3, but not non-phosphorylated STAT3, rescued glioblastoma cells from the induction of senescence combined with a restoration of SKP2 expression levels." (PMID 25412315, 2014). "Furthermore, the authors observed that PIAS3, an endogenous inhibitor of STAT3, was largely absent in human glioblastoma tissues." (PMID 25268165, 2014).
glioblastoma (continued). "Since we evidenced in glioblastomas that the amounts of CD44 are high and that the amount of SIRT1 that inactivates EP300 is low, we can assume that this situation may facilitate activation of STAT3 by acetylation." (PMID 21655185, 2011). "However, given the complexity of the tumour microenvironment within glioblastoma and the predominance of immunosuppressive macrophages and microglia, an enhanced inflammatory response especially involving IL-6/JAK/STAT3 pathways may enhance immunosuppression and inadequate T-cell response." (PMID 38227740, 2024). "RES could act its antitumor activity on glioblastoma CD133+ tumor-initiating cells by inhibiting cell viability and growth, blocking self-renewal capacity, inducing apoptosis, and enhancing radiosensitivity in vitro and in vivo through suppression of the STAT3 street." (PMID 35328780, 2022). "Consequently, downregulation of the PI3K-Akt/NF-κB/mTOR, STAT3, and CDK6 signaling pathways was reportedly used to abrogate GBM oncogenic properties and re-sensitized aggressive glioblastomas to chemotherapy." (PMID 34572040, 2021). "Recently, the degree of signal transducer and activator of transcription 3 (STAT3) activity has emerged as an important biomarker in targeted therapy of cancer patients, including glioblastoma patients, suggesting that STAT3 inhibitors may be an essential strategy for the treatment of glioblastoma." (PMID 32183406, 2020). "ICI non-responders were enriched in glioblastoma stem cells marked by SOX2 and PTPRZ1 and in cells marked by the IL-6 effector p-STAT3 in both pre- and post-ICI samples compared to ICI responders." (PMID 40161763, 2025). "We transfected U-87 MG cells, a human glioblastoma cell line lacking endogenous α receptor expression with a luciferase reporter responsive to STAT transcription factors (STAT1, STAT3, STAT5), a classical readout of PDGF receptor activity." (PMID 38532028, 2024). "It has been reported that TRIM8 cancels the negative effect of PIAS3 on STAT3 by degradation of PIAS3 and enhances Src-dependent tumorigenesis of glioblastoma." (PMID 38879600, 2024). "The same authors also found that the activation of STAT3, but not STAT5, was reduced in Rac-depleted glioblastoma cells." (PMID 34307396, 2021). "Using this approach, we identified HIF1A, STAT3 and SNAI2 (Slug) as the three most overexpressed migration-related transcription factors in human glioblastomas when compared to non-tumor brain." (PMID 20565806, 2010).
pancreatic cancer (663 papers, 2004 to 2026). "We employed multi‐omics analysis combined with cellular and animal experiments to examine the association between CTHRC1 and the LIF/STAT3 pathway in pancreatic cancer clinical specimens." (PMID 40751418, 2025). "Taken together, these findings indicate that KRAS mutations are one of major causative factors for STAT3-ZDHHC20 axis hyperactivation in pancreatic cancer." (PMID 38821916, 2024). "The activation of STAT3 signaling in pancreatic cancer is implicated in cell survival promotion, apoptosis inhibition (Glienke, Hausmann & Bergmann, 2011), and the upregulation of MMP7 expression, fostering cancer growth and metastasis." (PMID 38250721, 2024). "Mutation or acetylation of CDK1 at K33 weakened STAT3 phosphorylation at Y705, impairing the expression of stem-related genes and pancreatic cancer stemness." (PMID 37743465, 2023). "Using a dual recombinase mouse model of pancreatic cancer, investigators uncover genetic evidence for the role of STAT3 signaling in cancer-associated fibroblasts in promoting tumor progression and an immunosuppressive microenvironment." (PMID 35803738, 2022). "As this axis is highly expressed across various cancer types, the authors correlated it to epigenetics and immunity, and found an association between CAFs and STAT3 in pancreatic cancer." (PMID 35453676, 2022). "The authors reported that the use of MEK inhibitors such as AZD6244 and trametinib caused profound activation of STAT3 in K-Ras mutant pancreatic cancer." (PMID 36145523, 2022). "The development of metastases in pancreatic cancer was associated with ciRS-7 regulating miR-7-mediated EGFR/STAT3 signaling." (PMID 35313983, 2022). "Phosphorylation of signal transducer and activator of transcription 3 (STAT3) is enhanced by a stiff matrix in pancreatic cancer cells and is associated with shorter patient survival." (PMID 35205794, 2022). "Previous proteomic results have confirmed that the activation of tumor-associated fibroblasts (CAF) in pancreatic cancer is regulated by STAT3." (PMID 36291659, 2022). "Previous studies have reported that STAT3 is constitutively activated in patients with pancreatic cancer, and is associated with therapeutic resistance." (PMID 34771150, 2021). "Loss of STAT3 in lung and pancreatic cancers was associated with mesenchymal transition of epithelial cells and an aggressive tumour phenotype." (PMID 34047814, 2021). "So far, we discussed the evidence that P2X7R stimulation of PSCs causes the release of IL-6, which stimulates STAT3 signaling in pancreatic cancer cells." (PMID 34440697, 2021). "Our data in pancreatic cancer suggest a R248W allele-specific gain-of-function on migration via STAT3 deregulation." (PMID 34178628, 2021). "It was documented that the expression of JAK2 and STAT3 was particularly high in pancreatic cancer tissues compared with para-cancerous tissues and it was intensely associated with a poor prognosis in pancreatic cancer patients." (PMID 34623971, 2021). "PIMREG is known to positively regulate STAT3 activity to promote cell differentiation and shown to be associated with poor survival in the BC and pancreatic cancer." (PMID 33718103, 2020). "STAT3 knockdown was shown to be associated with increased response to gemcitabine in pancreatic cancer cells." (PMID 30065235, 2018). "Inhibition of the JAK/STAT3 pathway has been classically known as a mechanism of pancreatic cancer cytotoxicity caused by CuB." (PMID 29262554, 2017). "In gastric, colorectal and pancreatic cancer STAT3 promotes tumorigenesis and is associated with shortened survival." (PMID 28350325, 2017).
pancreatic cancer (continued). "Since JAK2, SOCS, JNK/SAPK, and Src signaling all converge and impinge on STAT3 signaling, our data suggests that loss of Cav-1 serves to reduce pancreatic cancer oncogenic proliferation, migration, invasion, and cell survival through a STAT3 mechanism." (PMID 26065715, 2015). "STAT3 activation promotes the oncogenic phenotype of pancreatic cancer, and loss of STAT3 prevents pancreatic cancer development and progression in a mouse model of Kras-mediated pancreatic cancer." (PMID 24015205, 2013). "STAT3 signaling has been implicated in pancreatic cancer biology, namely by mediating or regulating cell survival, tumor angiogenesis and metastasis." (PMID 23094050, 2012). "Previous reports have shown a close association between STAT-3 activation and pancreatic tumor growth and vascularization." (PMID 22016776, 2011). "The aim of the present study was to investigate the effects of STAT3 knockdown in nude mouse xenografts of pancreatic cancer cells and underlying gene expression." (PMID 21991388, 2011). "Previous reports have shown that phosphorylated STAT-3 is associated with over-expression of VEGF and HIF-1α in human pancreatic tumors and that inhibition of STAT-3 causes significant reduction in tumor growth and vascularization." (PMID 22016776, 2011). "Additionally, STAT3 hyperactivation has been implicated in cancer progression and poor prognosis in pancreatic cancer, prostate cancer, colorectal cancer, and esophageal cancer." (PMID 40075607, 2025). "Furthermore, increased STAT3 signaling has been linked to chemoresistance in pancreatic cancer and targeting STAT3 signaling synergizes with gemcitabine chemotherapy in mouse models of PDAC38." (PMID 37640930, 2023). "STAT3 not only directly regulates the target gene to promote the progression of pancreatic cancer, but also is associated with the formation of immunosuppressive microenvironment and the therapeutic resistance of pancreatic cancer." (PMID 37415745, 2023). "HO-3867 has previously been known to cause apoptosis to cancer cells through the targeting of several key growth-regulatory proteins such as the Janus kinase (JAK) as well as STAT3 pathway to cause apoptosis among oral, ovarian, endometrial, and pancreatic cancers." (PMID 35745828, 2022). "We believe that STAT3 may be an important factor in developing resistance to MEK inhibitors in K-Ras-mutated pancreatic cancer." (PMID 36145523, 2022). "Furthermore, EGFR feedback activation after STAT3 inhibition is the cause of resistance to therapy in pancreatic cancer." (PMID 35681787, 2022). "Unexpectedly, compound 4 appears to be a strong dual inhibitor of JAK/signal transducer and activator of transcription 3 (STAT3) and Src family of protein tyrosine kinases (SFKs)/STAT3 signaling that is associated with the induction of apoptosis in human pancreatic cancer cells." (PMID 34067242, 2021). "Hyper-activation of STAT3 has been associated with poor prognosis in pancreatic cancer patients." (PMID 33546207, 2021). "However, aberrant or constitutively activated STAT3 has been observed in many different cancers, such as colorectal, lung, breast, prostate, liver, and pancreas cancers, and STAT3 activation associates with poor prognosis of these cancers." (PMID 32422984, 2020). "Importantly, STAT3 is required for the evolution of pancreatic neoplasia into pancreatic cancer in the presence of KRAS mutations." (PMID 31796877, 2019). "In previous studies from our laboratory, we found a marked decrease in the levels of DNA binding activity by the active and inactive forms of STAT3, an inflammatory mediator, which was associated with proliferation inhibition in pancreatic cancer cells after treatment with Nx." (PMID 24796733, 2014). "Constitutive STAT3 activation is a hallmark of many human cancers, including pancreatic cancer." (PMID 24015205, 2013).